TTF1 (transcription termination factor 1)
Diseases named in the same sentence as TTF1 in open-access papers (continued):
Sharing a sentence is not in itself a finding about the gene and the disease.
diabetes (2 papers, 2018 to 2023). "Furthermore, another study also showed that streptozotocin-induced reduction of SP-A expression was prevented by liraglutide through the TTF-1 signaling pathway in a rat model of diabetes." (PMID 29950925, 2018). "Furthermore, the investigation of how TTF-1 is dysregulated in conditions such as obesity, diabetes, or eating disorders may uncover potential therapeutic targets for modulating energy balance and metabolic health." (PMID 37569904, 2023).
endometrial adenocarcinoma (2 papers, 2022 to 2023). "Poorly differentiated endometrial adenocarcinoma was histologically similar to H-FLAC, but in immunohistochemistry, endometrial adenocarcinoma was positive for ER, PR, and vimentin, but negative for TTF-1 expression." (PMID 35356917, 2022).
giant cell carcinoma (2 papers, 2017 to 2024). "Unlike in giant cell carcinoma, the absence of thyroid transcription factor 1 (TTF-1) immunoreactivity in PPC facilitated accurate differentiation." (PMID 39077298, 2024).
granulosa cell tumor (2 papers, 2021). A slow-growing, malignant tumor, characterize by the presence of granulosa-like cells and Call-Exner bodies, that is almost always found in the ovary. "TTF-1 is also positive in spindle cell oncocytoma and granulosa cell tumors." (PMID 34210357, 2021).
lung disease (2 papers, 2018 to 2022). "Additionally, it is reported that haploinsufficient mutations in TTF-1 are associated with pulmonary disease in infants and with variable inhibitory effects on the expression of SPs in human." (PMID 29950925, 2018).
metastatic colorectal cancer (2 papers, 2017 to 2025). "This case highlights a potential diagnostic pitfall in metastatic colorectal cancer: aberrant TTF-1 expression can mimic a primary lung tumor." (PMID 41310725, 2025). "Immunocytochemical positivity for CK20 and CDX-2 and negativity for CK7, CK5/6, P63 and TTF-1 confirmed this to be metastatic colorectal cancer." (PMID 29029440, 2017).
mucoepidermoid carcinoma of lung (2 papers, 2012). "Previous studies examined the expression of TTF-1 in a small numbers of mucoepidermoid carcinomas of the lung." (PMID 23043986, 2012).
neuroblastoma (2 papers, 2011 to 2025). Neuroblastoma (NB) is the most common solid, extracranial childhood tumor. "Promoter assays showed that TTF-1 inhibits COX-2 transcription in the glial cells but not in the neuroblastoma cells." (PMID 22174936, 2011).
Obesity (2 papers, 2023 to 2025). Accumulation of substantial excess body fat. "The PTSD hubs, SHCBP1 and TTF1, were predicted to indirectly receive signals from the regulatory signatures of obesity and smoking." (PMID 40102990, 2025).
pancreatic neoplasm (2 papers, 2024). A benign or malignant neoplasm involving the pancreas. "In the patient's case, the tumor's immunohistochemical profile, specifically being TTF-1 positive (associated with pulmonary tumors) and CDX2 negative (associated with GI and pancreatic tumors), strongly suggests a lung origin." (PMID 39130860, 2024).
papillary adenoma (2 papers, 2013 to 2020). An adenoma characterized by the presence of papillary epithelial patterns. "A papillary adenoma, however, consists of fibrovascular cores lined by cuboidal or columnar epithelium and it is positive for TTF-1, whereas an alveolar adenoma containing TTF-1 positive cells shows cystic-like spaces lined by cuboidal cells." (PMID 23533890, 2013).
papillary renal cell carcinoma (2 papers, 2014 to 2024). A rare subtype of renal cell carcinoma, arising from the renal tubular epithelium and showing a papillary growth pattern, which typically manifests with hematuria, flank pain, palpable abdominal mass or nonspecific symptoms, such as fatigue, weight loss or fever. "The tumour was positive for PAX8 and negative for TTF-1 indicating the renal origin of the tumour while positivity for AMACR & CK7 confirmed the diagnosis of papillary renal cell carcinoma." (PMID 38265103, 2024).
peritoneal effusion (2 papers, 2016 to 2023). "The role of thyroid transcription factor 1 (TTF-1) in the diagnosis of metastatic pulmonary adenocarcinomas in pleural, pericardial, and peritoneal effusions has not been defined." (PMID 26806377, 2016). "However, the role of TTF-1 in cytology preparations has rarely been recognized, and immunohistochemistry was used to investigate the expression of TTF-1 in malignant pleural and peritoneal effusion." (PMID 37675165, 2023).
pituitary neoplasms (2 papers, 2020 to 2024). "The expression of thyroid transcription factor-1 (TTF-1) in these tumors aids in distinguishing them from other pituitary neoplasms." (PMID 39353313, 2024).
pleural mesothelioma (2 papers, 2022 to 2024). A neoplasm that arises from the mesothelial cells of the pleura. "TTF-1 IHC is widely used by pathologists for the distinction of primary pulmonary adenocarcinoma—typically TTF-1 positive—from pulmonary squamous cell carcinoma, metastatic adenocarcinoma to the lung, and pleural mesothelioma which are TTF-1 negative in most cases." (PMID 39377914, 2024).
pneumonia (2 papers, 2019 to 2020). An acute, acute and chronic, or chronic inflammation focally or diffusely affecting the lung parenchyma, caused by an infection in one or both of the lungs (by bacteria, viruses, fungi, or mycoplasma.). "In addition, in this group of cases, the expression of TTF-1 in pneumonia-type IMA was mostly negative, with only one positive case, which may be related to the advanced stage of the pneumonia-type IMA." (PMID 31292000, 2019).
posterior pituitary tumors (2 papers, 2021 to 2025). "According to the 2025 WHO classification, SCO represents one of four recognized subtypes of posterior pituitary tumors derived from pituicytes, unified by diffuse nuclear TTF-1 expression and a shared origin from the ventral neuroectoderm." (PMID 40648926, 2025). "According to the 2025 WHO classification, GCTs are recognized as one of the four subtypes of posterior pituitary tumors derived from pituicytes, unified by diffuse nuclear TTF-1 expression and a shared origin from ventral neuroectoderm." (PMID 40648926, 2025). "Interestingly, the closest neighbors of posterior pituitary tumors were the other two TTF1 expressing tumor groups SEGA and chordoid glioma." (PMID 34661724, 2021).
prostate adenocarcinoma (2 papers, 2024 to 2025). "Immunohistochemistry was negative for CK20, CK5/6, PAX-8, TTF-1, PSA, and PIN4, but positive for PSAP and NKX3.1, consistent with mucin-producing prostate adenocarcinoma." (PMID 41293260, 2025). "Immunohistochemical analysis revealed these atypical cells did not express general thyroid markers (PAX8 and TTF1), but rather expressed the prostate markers NKX3.1 and PSA, confirming the presence of prostate adenocarcinoma which had metastasized to the known thyroid gland nodule." (PMID 38879699, 2024).
rectal adenocarcinoma (2 papers, 2018 to 2020). "We present the case of a patient with rectal adenocarcinoma with lung metastasis found to be TTF-1-positive on immunohistochemistry." (PMID 30631609, 2018). "In contrast, the tumor cells in the PTC were positive for TTF-1 and PAX8, but negative for rectal adenocarcinoma marker." (PMID 32375670, 2020). "The tumor cells of metastatic rectal adenocarcinoma were positive for gastrointestinal markers CDX2, CK20 and Villin but were negative for TTF-1 and PAX8." (PMID 32375670, 2020).
serous carcinoma (2 papers, 2021 to 2025).
thymic adenocarcinoma (2 papers, 2021 to 2023). "Previous studies on thymic adenocarcinoma showed that most cases were positive for cytokeratin 7 and CD5 and negative for PAX8 and TTF1." (PMID 39790334, 2023). "PAX8, TTF1, c-KIT, and napsin A were negative, indicating thymic adenocarcinoma." (PMID 39790334, 2023).
ameloblastoma (1 paper, 2015). The most common odontogenic tumor, arising from the epithelial component of the embryonic tooth and usually affecting the molar-ramus region of the mandible or maxilla. "Only the pulmonary metastastic lesions were CK7+, TTF1+ and PE10+, which highlighted the glandular/papillary structures composed of hyperplastic alveolar epithelial cells that may have been stimulated by the non-destructive growth of the ameloblastoma." (PMID 26205138, 2015).
atypical carcinoid tumor (1 paper, 2023). A carcinoid tumor characterized by a high mitotic rate, often associated with the presence of necrosis and nuclear pleomorphism. "In summary, atypical carcinoid tumor in the mediastinum, especially with ACTH ectopic syndrome and TTF-1 positivity is very rare." (PMID 37266641, 2023).
breast phyllodes tumor (1 paper, 2021). A benign, malignant, or borderline circumscribed biphasic neoplasm that arises from the breast. "Metastatic breast phyllodes tumors can also show phyllodes structures, but they can be differentiated based on ER, PR, TTF-1 and Napsin A staining and clinical history." (PMID 34350112, 2021).
bronchiectasis (1 paper, 2020). Segmental, irreversible dilation of the bronchial tree resulting in the accumulation of secretions which leads to obstruction. "We noted two main types of epithelial hyperplasia with disarrangement of TTF-1+ cells: cuboidal (100%) and columnar (93.0%) among the 43 bronchiectasis patients." (PMID 32154248, 2020). "In airway sub-epithelium of the dilated bronchioles, epithelial hyperplasia with disarrangement of TTF-1+ cells yielded cuboidal (100%) and columnar (93.0%) type among bronchiectasis patients." (PMID 32154248, 2020). "We noted a significantly lower percentage of TTF-1+ECs and CC10+ECs and higher percentage of P63+ECs in bronchiectasis patients compared with control subjects (all P < 0.05)." (PMID 32154248, 2020). "Compared with control subjects, significantly decreased percentage of TTF-1+ECs and CC10+ECs and a higher percentage of P63+ECs were identified in the dilated bronchioles in bronchiectasis (all P < 0.05)." (PMID 32154248, 2020). "Notably, we have identified the aberrant expression of progenitor cell markers (TTF-1, P63, and CC10) in bronchiolar epithelium in bronchiectasis." (PMID 32154248, 2020).
bronchioalveolar carcinoma (1 paper, 2012). "TTF-1 is positive in the vast majority of conventional pulmonary adenocarcinomas including nonmucinous type bronchioalveolar carcinoma (BAC)." (PMID 23119210, 2012).
cervical carcinoma (1 paper, 2025). A carcinoma arising from either the exocervical squamous epithelium or the endocervical glandular epithelium. "The metastatic thyroid lesion exhibited strong p16 positivity and morphological features identical to the primary cervical carcinoma, while TTF-1 negativity confirmed its origin as metastatic HPV-related cervical cancer." (PMID 41479925, 2025).
cervical small cell carcinoma (1 paper, 2025). A small cell carcinoma arising from the cervix. "At this time, TTF-1 cannot serve as a diagnostic marker for differential diagnosis, as both esophageal and cervical small cell carcinomas can be TTF-1 positive." (PMID 41305788, 2025).
colitis (1 paper, 2023). Inflammation of the colon. "Gene expression of the regulatory proteins Abca3 and Ttf1 were also increased and there were trending differences between C57BL/6 and TCRδ-/- mice with colitis." (PMID 37063825, 2023).
ductal carcinoma in situ (1 paper, 2010). "The presence of ductal carcinoma in situ with positive TTF-1 is a strong indication that this is a primary tumour and not a metastasis from lung." (PMID 20565809, 2010).
ear tumors (1 paper, 2015). "On the other hand, thyroid transcription factor-1 (TTF-1 or NKx2.1) was not expressed in ear tumors, indicating that these tumors were not metastatic from lung or thyroid tissues." (PMID 26027747, 2015).
endometrial tumors (1 paper, 2021).
esophageal adenocarcinoma (1 paper, 2025). A malignant tumor with glandular differentiation arising predominantly from Barrett mucosa in the lower third of the esophagus. "Here, 3% of 65 esophageal adenocarcinomas were TTF-1-positive, partly with weak staining and partly with strong staining." (PMID 40564811, 2025). "In detail, five cases (5/125; 4%) of esophageal adenocarcinomas showed positive staining for TTF-1, three cases (3/125; 2.4%) showed positive staining for Napsin A and were both TTF-1- and Napsin A-positive." (PMID 40564811, 2025). "In Nelson G. Ordonez’s review article, no TTF-1 positivity in esophageal adenocarcinomas was reported; however, IHC was applied in only three cases." (PMID 40564811, 2025).
esophageal SCC (1 paper, 2007). "Higher percentages of positive labeling of Syn, CD56, CgA, NSE, and TTF-1 in esophageal SCC cases implicated that they are valuably applied in differential diagnosis of the malignancy." (PMID 17335582, 2007). "In the present study, 71.4% of esophageal SCC cases were positive for TTF-1, which was higher than the previously reported rate." (PMID 17335582, 2007). "Higher proportion of positive labeling of Syn, CD56, CgA, NSE, and TTF-1 in esophageal SCC implicate that they are valuably applied in differential diagnosis of the malignancy." (PMID 17335582, 2007). "We confirmed that TTF-1 showed higher positive labeling in primary esophageal SCC, suggesting that it was a suitable marker for diagnosis and differentiation of esophageal SCC." (PMID 17335582, 2007).
gastric polyp (1 paper, 2024). "Similarly, the previous pathology result of gastric polyp had tumor cells staining diffusely and strongly with CK7, Napsin, and TTF-1; patchy weak staining of CDX2; and negative for CK20." (PMID 39176211, 2024).
Hirschsprung disease (1 paper, 2016). Hirschsprung disease (HSCR) is a congenital intestinal motility disorder that is characterized by signs of intestinal obstruction due to the presence of an aganglionic segment of variable extent in the terminal part of the colon. "It was recently shown that TTF-1 is also involved in the transcription of human RET in Hirschsprung’s disease." (PMID 27409604, 2016). "The role of TTF-1 in the development of Hirschsprung’s disease by RET interaction has been recently outlined." (PMID 27409604, 2016). "Thyroid transcription factor-1 (TTF-1) is involved in rearranged during transfection (RET) transcription in Hirschsprung’s disease." (PMID 27409604, 2016).
Hydrocephalus (1 paper, 2025). Hydrocephalus is an active distension of the ventricular system of the brain resulting from inadequate passage of CSF from its point of production within the cerebral ventricles to its point of absorption into the systemic circulation. "Other variables, such as the location of the dominant brain metastasis, the incidence of hydrocephalus, and the intracranial brain metastasis burden, did not significantly differ between TTF-1- and TTF-1 + patients." (PMID 39630375, 2025).
hypopituitarism (1 paper, 2011). A condition of diminution or cessation of secretion of one or more hormones from the anterior pituitary gland. "Hence, in our case pituitary malformation is presumably caused by TTF-1 signaling disruption, leading to central hypopituitarism and GH deficiency." (PMID 21867529, 2011).
infiltrating ductal carcinoma (1 paper, 2010). "We have presented an unusual case of TTF-1 positive primary infiltrating ductal carcinoma with focal basal-like and neuroendocrine differentiation." (PMID 20565809, 2010).
invasive carcinoma (1 paper, 2017). A carcinoma that is not confined to the epithelium, and has spread to the surrounding stroma. "A vertebral biopsy was performed finding an invasive carcinoma, CK7+/CK20+, TTF1-, PSA-, Thyroglobulin- and GATA3+." (PMID 28494780, 2017).
large cell lung carcinoma (1 paper, 2024). "Based on 2015 WHO classification criteria in redefining large cell lung carcinoma, the expression of specific markers (TTF1, Napsin A, P 40, CK5/6, CK, vimentin and ZEB1) is analyzed by immunohistochemistry." (PMID 39064008, 2024).
leiomyosarcoma (1 paper, 2016). An uncommon, aggressive malignant smooth muscle neoplasm, usually occurring in post-menopausal women. "In the cases presented, the fact that negative staining of the tumor with thyroglobulin, TTF-1, and keratin, and that positive staining was observed with vimentin and actin in the first case specimen, led to the immunohistopathological diagnosis of leiomyosarcoma." (PMID 27080750, 2016).
lentivirus infection (1 paper, 2021). Virus diseases caused by the Lentivirus genus. "To investigate the effects of TTF1, we modified TTF1 expression in cell lines and in the ARC or AVPV nucleus of 21-day-old female rats via lentivirus infection." (PMID 33622350, 2021).
leptospirosis (1 paper, 2013). A contagious bacterial infection caused by spirochetes of the genus Leptospira. "In leptospirosis, pneumocytes expressing the TTF1 antibody were agreggated as small cellular groups or isolated cells, observed at the periphery of the hemorrhagic and edematous regions." (PMID 23951234, 2013). "It showed a slight decrease in the number of TTF-1 positive cells, chiefly in leptospirosis, which was more severe when compared to the peripheral areas of sepsis and the controls." (PMID 23951234, 2013).
meningioma (1 paper, 2020). A generally slow growing tumor attached to the dura mater. "According to the available immunohistochemical results of published cases, the meningioma components were often positive for EMA, PR, and vimentin (except for 1 case of secretory meningioma), and the pulmonary carcinoma components were frequently positive for TTF-1 and CK7." (PMID 33126391, 2020). "The focus within the meningioma stained positive for cytokeratin 7 (CK7) and thyroid transcription factor 1 (TTF-1) and negative for CK5/6, p63, CD56, and synaptophysin." (PMID 33126391, 2020).
mesonephric adenocarcinoma (1 paper, 2025). An adenocarcinoma of the cervix or the vagina arising from mesonephric remnants. "Mesonephric adenocarcinoma characteristically expresses mesonephric markers such as GATA3, TTF1, and PAX2, while lacking hormone receptor expression." (PMID 40647429, 2025).
metastatic squamous cell carcinoma (1 paper, 2023). A squamous cell carcinoma which has spread from its original site of growth to another anatomic site. "In our case, the patient had TTF-1 (-), CK7 (+), and P40 (+), so metastatic squamous cell carcinoma was highly likely." (PMID 37710181, 2023).
mucoepidermoid carcinomas of the (1 paper, 2012). "Here, we reported a special and rare case of mucoepidermoid carcinoma with TTF-1 and SP-B positive glandular epithelial cells, which required attention in differential diagnosis." (PMID 23043986, 2012). "They showed that all mucoepidermoid carcinomas of the bronchus in their series were negative for TTF-1." (PMID 23043986, 2012). "It was reported that the expression of TTF-1 was negative in the mucoepidermoid carcinomas of sinonasal tract (19 cases), But was positive in the mucoepidermoid carcinomas of thyroid gland (2 of 4 cases)." (PMID 23043986, 2012).